TNF (tumor necrosis factor)
Diseases named in the same sentence as TNF in open-access papers (continued):
Sharing a sentence is not in itself a finding about the gene and the disease.
peritonitis (continued). "In an acute model of sterile inflammation using a murine model of pristane-induced peritonitis the IFN-I signaling was responsible for monocyte recruitment and maturation during inflammation while mice deficient in TLR4, TNFα, IL-6, and IL1R failed to accumulate monocytes in the peritoneal cavity." (PMID 33995391, 2021). "However, DEXA reduced the pro-inflammatory cytokines (IL-1β and TNF-α) but did not increase IL-10 levels in peritoneal fluid of mice with peritonitis." (PMID 21799673, 2011). "Dopamine-mediated DRD1 signaling also prevents both LPS-induced systemic inflammation and MSU-induced peritonitis through suppression of IL-1β production via inhibition of NLRP3 inflammasome activation, but not by suppression of TNF-α." (PMID 29868015, 2018). "Moreover, peritoneal MØs isolated from patients under CAPD during peritonitis episodes exhibit increased proinflammatory cytokines expressions, such as IL-1β and tumoral necrosis factor (TNF)-α, compared to macrophages from CAPD patients without peritonitis." (PMID 36982834, 2023). "This conclusion was supported by classic analyses using the Mann-Whitney U test showing that levels of Vγ9+ and Vδ2+ T cells and TNF-α, but not of IL-12p40 and VEGF, were markedly different between patients with Gram-negative infections and patients with other episodes of peritonitis." (PMID 28318629, 2017).
Salmonella Infections (154 papers, 2004 to 2026). Infections with bacteria of the genus SALMONELLA. "Wallis et al40 have identified 11 cases of anti-TNF-associated Salmonella infection (7 cases with infliximab and 4 cases with etanercept) from the FDA’s AERS." (PMID 26425605, 2014). "The central role of TNF-α was further supported by genetic study that TNFRp55-deficient mice were highly susceptible to Salmonella infection." (PMID 22470519, 2012). "The rice bran fed mice showed a significant reduction in serum inflammatory cytokines associated with Salmonella infection, namely TNF-α, IFN-γ and IL-12." (PMID 22583915, 2012). "In addition, macrophages from coinfected pigs showed enhanced susceptibility to Salmonella infection in vitro and the Salmonella-induced monocytosis and tumor necrosis factor alpha production by myeloid cells was repressed in pigs coinfected with Ascaris." (PMID 39140728, 2024). "In addition, we measured the levels of additional cytokines (IL-10 and TNF-α) associated with Salmonella infections." (PMID 34484221, 2021). "Induction of pro-inflammatory cytokines, such as tumor necrosis factor-alpha (TNF-α) and interleukin-1 beta (IL-1β), following Salmonella infection in tumor-bearing hosts is indicative of host-mediated tumoricidal effects." (PMID 39873483, 2025). "Prevotellaceae_NK3B31_group was negatively correlated with TNF-α expression and salmonella infection." (PMID 41301940, 2025). "It has been established that during early Salmonella infection, inflammatory monocytes produce anti-microbial factors such as TNF-α and IL-1β." (PMID 40014608, 2025). "The Salmonella infection significantly altered mRNA levels of pro-inflammatory cytokines (IL-6, IL-1α, IL-1β, and TNF-α)." (PMID 38667028, 2024). "Salmonella infection triggers the release of cytokines such as IL-6, IL-1β and TNF-α, resulting in systemic inflammatory stress." (PMID 38715123, 2024). "Salmonella infection in chickens increases the serum concentrations of IgG and IgA and IL-1β, IL-6, and TNF-α." (PMID 38053560, 2023). "Salmonella infection increased the expression of IL-1β, IL-6, and TNF-α in the jejunal and ileal mucosa of broilers." (PMID 38053560, 2023). "Differentially expressed genes (DEGs) between subtypes were mainly enriched in immune-related pathways such as TNF signalling pathway and Salmonella infection." (PMID 37353728, 2023). "The results of KEGG pathway analysis showed that the DE-NRGs were mainly enriched in Necroptosis, Salmonella infection, Apoptosis, and TNF signaling pathway." (PMID 37091800, 2023). "KEGG enrichment analysis results showed that the DEGs were mainly enriched in Ribosome, TNF signalling pathway and Salmonella infection." (PMID 37353728, 2023). "Kyoto Encyclopedia of Genes and Genomes pathway analysis revealed that DEGs were enriched in cytokine–cytokine receptor interaction, Chagas disease, tumor necrosis factor (TNF) signaling pathway, Salmonella infection, and NF-kappa B signaling pathway." (PMID 36932450, 2023). "Salmonella infection significantly increased the ileal contents of inflammatory cytokines (IL-1β, IL-6, IL-8, TNF-α, IFN-β and IFN-γ) compared with the CON." (PMID 36670458, 2023). "Salmonella infection induces TNF expression and hence provides an endogenous source of TNF within the intestinal tract." (PMID 37598207, 2023). "In the context of Salmonella infection, TNFα appears to drive widespread pathological death and dislodgement of IECs at 72 hr post-infection." (PMID 36645406, 2023). "Differentially expressed genes between subtypes were mainly enriched in immune-related pathways such as ‘Ribosome’, ‘TNF signalling pathway’ and ‘Salmonella infection’." (PMID 37353728, 2023).
Salmonella Infections (continued). "In KEGG pathway analysis, we learned that these genes are mainly concentrated in Necroptosis, Salmonella infection, and TNF signaling pathway." (PMID 36506314, 2022). "Salmonella infection robustly induces proinflammatory cytokines, including tumor necrosis factor (TNF-α) and interleukin 6 (IL-6), and triggers caspase-1-dependent proinflammatory programmed cell death (8, –, 10)." (PMID 35579463, 2022). "The results showed that OP-related genes mainly enriched the MAPK signaling pathway, TNF signaling pathway, apoptosis, and Salmonella infection." (PMID 36311708, 2022). "The results revealed that Salmonella infection up-regulated all studied pro-inflammatory cytokines such as TNF-α, IL-8, IL-6 and TLR4, TLR5 signaling pathways, while decreasing the expression of TGF-β." (PMID 36556320, 2022). "The level of TNFα in plasma was significantly higher in the Salmonella infection group compared with the control group, while the level of IL-10 in plasma was significantly lower in the Salmonella infection group compared with that of the control group." (PMID 35163196, 2022). "Salmonella infection triggers a signal for the expression of a diverse range of inflammatory cytokines, such as TNF-α, IL-1β, and IFN-γ." (PMID 36183131, 2022). "A previous study reported that a number of cytokines, including IL-1β and TNF-α, are produced during the initial salmonella infection." (PMID 35371085, 2022). "Salmonella infection can lead to mild intestinal inflammation, which releases cytokines and other factors like interleukin-6 (IL-6), IL-8, IL-12, LPS-induced tumor necrosis factor alpha (LITAF) and interferon gamma (IFN-γ)." (PMID 36311708, 2022). "Enrichment analysis showed these genes were mainly related to MAPK signaling pathways, TNF signaling pathway, apoptosis, and Salmonella infection." (PMID 36311708, 2022). "The results of KEGG pathway analysis showed DEMAmRNAs mainly regulate the biosynthesis of amino acids, homologous recombination, B cell receptor signaling pathway, salmonella infection, spliceosome, TNF signaling pathway, Carbon metabolism, and so on." (PMID 34055638, 2021). "From the KEGG enrichment results, three hub genes were significantly enriched in the following pathways: Chemokine signaling pathway, Cytokine-cytokine receptor interaction, Legionellosis, Salmonella infection, and TNF signaling pathway." (PMID 34269159, 2021). "There had been an interaction between heat stress and Salmonella infection in the expressions of TNF-α, IL-6, IL-1β, pro-IL-1β, and NLRP3." (PMID 34061266, 2021). "Next, KEGG pathway analysis of these DEGs presented IL-17 signaling, TNF signaling pathway, Salmonella infection, revealing their potential roles for the pathogenesis of COPD." (PMID 34220411, 2021). "Multiple immunomodulators and proinflammatory cytokines have protective roles against salmonella infections such as interleukins (IL)-1alpha, tumor necrosis factor (TNF) alpha, interferon gamma (IFN-γ), IL-12, IL-18, and IL-15." (PMID 33396722, 2020). "The KEGG pathways Cytokine-cytokine receptor interaction, TNF signaling pathway and salmonella infection were significantly enriched in NCI-N87 cells after 4 h afatinib treatment (p.adjust < 0.05)." (PMID 33115415, 2020). "RNA-sequencing identified 513 DEGs in infected cells, with specific differential regulation in mRNA involved in tight junction signaling, TNF signaling, salmonella infection response, and immune response, among other important cellular processes." (PMID 32140061, 2020). "Pathways were analyzed using the Kyoto Encyclopedia of Genes and Genomes database, and the result revealed that most significant enrichment pathways were related to immune responses, which included Salmonella infection, TNF, Toll-like receptor, NF-κB, etc.." (PMID 33297958, 2020).
Salmonella Infections (continued). "KEGG enrichment analysis indicated that the IRGs were enriched in the following five KEGG terms: cytokine-cytokine receptor interaction, chemokine signaling pathway, legionellosis, salmonella infection, and TNF signaling pathway." (PMID 32756008, 2020). "In cluster 5, the DEGs were primarily connected to chemokine signalling, Legionellosis, Salmonella infection, TNF signalling and cytokine‐cytokine receptor interactions." (PMID 31845522, 2020). "Salmonella infection has also been shown to increase the expression of TNF-α, which is a potent pleiotropic inflammatory cytokine, in vitro and in vivo; therefore, it is often associated with many diseases including inflammation." (PMID 32150574, 2020). "Since Salmonella infection induces an increase in TNFα production, the effect of infection on paracellular permeability can be, in part, attributed to this cytokine." (PMID 33379352, 2020). "The ability of Salmonella infection to induce tumor necrosis factor (TNF) production in epithelial cells and macrophages is well-documented." (PMID 31402916, 2019). "Briefly, most enriched pathways were related to the TNF signaling pathway, Salmonella infection, Pertussis, MAPK signaling pathway, cytokine-cytokine receptor interaction, Influenza A, and Amoebiasis." (PMID 30863688, 2019). "It is likely that when gut-resident Mφ fail to contain the Salmonella infection they release cytokines/chemokines (e. g., IL-6, IL-8, TNF-α, and CCL3) to attract more macrophages and PMN to the diseased area." (PMID 31412039, 2019). "Despite altered bacterial clearance, control macrophages and butyrate macrophages displayed similar expression of IL1B and TNF mRNA and protein following 3 h of Salmonella infection, whereas IL10 expression was reduced in butyrate macrophages." (PMID 30683619, 2019). "The most enriched pathways in PCV2 infection include the TNF signaling pathway, Salmonella infection, Pertussis, MAPK signaling pathway, cytokine-cytokine receptor interaction, Influenza A, and Amoebiasis." (PMID 30863688, 2019). "This miRNA is an important regulator of inflammatory response during Salmonella infection, given that miR-125 has been reported as target of TNF-α, and its downregulation is required for proper TNF-α production." (PMID 29391047, 2018). "The upregulation of IFN-γ and TNF in serum and their roles in gene regulation indicate their important roles in Salmonella infection in pig." (PMID 30541630, 2018). "CCL20 expression can be promoted by producing the proinflammatory cytokines TNF-α and IL-1β during Salmonella infection." (PMID 28770173, 2017). "Murine models have shown that tumor necrosis factor alpha (TNFα) is an important mediator in host resistance to Salmonella infections." (PMID 28087648, 2017). "Pro-inflammatory cytokines such as interleukin (IL)-6, IL-1β (also called IL-1 F2), IL-18 and tumor necrosis factor (TNF)-α are released during early Salmonella infection." (PMID 25115174, 2014). "Early during Salmonella infection, immune cells including macrophages, granulocytes and lymphocytes are central to control bacterial replication by producing IL-6, TNF, IFN-γ and IL-12." (PMID 24505352, 2014). "They concluded that as recognition of microorganisms by TLR-4 and activation of phagocytes by IFN-γ are crucial mechanisms for the defence against intracellular pathogens, their inhibition by anti-TNF leads to severe complication with Salmonella infections." (PMID 26425605, 2014). "Salmonella infection reduced the constitutive expression of TNF-α and IL-4 mRNA in CD1b- L-DCs, whereas this expression was not affected by helminth secretions." (PMID 24223964, 2013). "This constitutive production of TNF-α and IL-4 reduced significantly 6h after Salmonella infection, whereas it was maintained 6h after Hc-ES stimulation, and then decreased 12h later (data not shown)." (PMID 24223964, 2013).
Salmonella Infections (continued). "Previous research demonstrated that in response to primary Salmonella infection, the host immune system releases massive amounts of the cytokines such as TNF-α, IFN-γ and IL-12 locally and systemically." (PMID 22583915, 2012). "Wild-type Salmonella infection also led to activation of these same genes although the expression of TNFα and MCP1 was transient in comparison and occurred immediately after infection." (PMID 15324458, 2004). "Compared to the CON, clove extract and eugenol notably reduced the expression levels of pro-inflammatory cytokines IL-1β, IL-6, and TNF-α in the jejunal tissue and crypts of yellow feather broilers; Salmonella infection significantly elevated the levels of these inflammatory factors." (PMID 40059168, 2025). "Among the KEGG terms, the result showed that GPC-1 was enriched with salmonella infection, endocytosis, and shigellosis with P value < 0.05, and these genes were mapped to neurotrophins signaling pathway, TNF signaling pathway, and sphingolipid signaling pathway." (PMID 38982153, 2024). "The KEGG results indicated that salmonella infection and the TNF signaling pathway might participate in the pathogenesis of AD." (PMID 35615282, 2022). "However, preincubation of intestinal epithelial cells with the WT GG strain and the mutant CMPG5230 were equally effective in reducing IL-8 and TNF-α expression in response to Salmonella infection." (PMID 36430834, 2022). "The immune responses following Salmonella infection in mice and humans have been reported as Th1-skewed phenotypes, which were a requisite for resolving infection of intracellular organisms via macrophage-activating cytokines such as IFNγ and TNFα." (PMID 33804435, 2021). "We and others have found that SseK1 and SseK3 could inhibit TNF-induced cell death during Salmonella infection." (PMID 32432056, 2020). "Another study showed that probiotic Lactobacillus efficiently reduced Salmonella infection and gut inflammation by increasing the levels of propionic acid and mucin-2, as well as changing the level of tumor necrosis factor-alpha (TNF-a), interleukin-10 (IL-10) and myeloperoxidase (MPO) in mice." (PMID 32150574, 2020). "In this study, we have shown that SLAMF9‐deficient mice have impaired clearance of systemic Salmonella infection, and suppression of SLAMF9 expression in human THP‐1 cells dramatically reduces their ability to produce pro‐inflammatory cytokines TNF‐α, IL‐1β and GM‐CSF." (PMID 31880316, 2020). "Moreover blocking of TNFα by administration of anti-TNFα antibodies prior to S. Typhimurium infection reduced gastrointestinal pathology, suggesting a rather harmful function of TNFα in the early phase of Salmonella infection." (PMID 30995806, 2019). "Salmonella infection significantly increased the production of TNF-α in the mouse colon." (PMID 30842764, 2019). "Neutralization of TNFα in the chronic phase of a Salmonella infection results in the regression of already established lesions and the reactivation of bacterial growth and spread in the tissues (Mastroeni, Villarreal-Ramos and Hormaeche 1993; Mastroeni, Skepper and Hormaeche 1995)." (PMID 28087648, 2017). "We tested whether the anti-inflammatory/immunosuppressive anti-TNFα treatment would have a synergistic or detrimental effect on an already established Salmonella infection when started simultaneously in a therapeutic combination with an antibiotic." (PMID 28087648, 2017). "Hence, these TNF-α or IFN-γ networks further reflect the pleiotropic action of proinflammatory cytokine involved in host defense against Salmonella infection by regulating extensive biological process." (PMID 21172007, 2010). "In addition, Salmonella infection is known to induce TNF production in macrophages and TNF has been reported to enhance IFN-γ production." (PMID 20027291, 2009).